RHOA (ras homolog family member A)
Diseases named in the same sentence as RHOA in open-access papers (continued):
Sharing a sentence is not in itself a finding about the gene and the disease.
osteoarthritis (10 papers, 2020 to 2026). A noninflammatory degenerative joint disease occurring chiefly in older persons, characterized by degeneration of the articular cartilage, hypertrophy of bone at the margins and changes in the synovial membrane. "In addition to Rac-1 activation, IL-1β-induced activation of RhoA has been associated with several types of chronic inflammatory disorders, including osteoarthritis (OA)." (PMID 41596581, 2026). "The persistent activation of both Rac-1 and RhoA by IL-1β contributes to chronic inflammatory diseases, including osteoarthritis (OA)." (PMID 41596581, 2026). "Consequently, we report for the first time that nesfatin-1 plays a crucial role in preventing the exacerbation of osteoarthritis by restoring cytoskeleton integrity of chondrocytes and suppressing excessive autophagy level via inhibiting the RhoA/ROCK pathway." (PMID 36859270, 2023). "Furthermore, an immunoprecipitation-based proteomics approach in samples from healthy and osteoarthritis patients revealed that Cx43 interacts with RhoA." (PMID 32070020, 2020). "In addition, various Cx43-interacting proteins are responsible for the development of several human diseases, among which RhoA has been previously reported to differ between healthy and osteoarthritis samples." (PMID 32070020, 2020). "Rutin is found to negatively regulate RhoA/ROCK signaling by promoting the expression of CBS, effectively inhibiting the inflammatory progression of osteoarthritis." (PMID 37938371, 2024).
schizophrenia (10 papers, 2013 to 2025). A major psychotic disorder characterized by abnormalities in the perception or expression of reality. "Mouse models have been developed based on schizophrenia-associated genetic variants involved in small GTPase RhoA signaling, including variants affecting the Arhgap10, Kalrn, and Rtn4r genes, and their phenotypic characterization has been performed." (PMID 37958606, 2023). "In this review, we summarize clinical evidence showing that variants in genes regulating RhoA activity are associated with schizophrenia." (PMID 37958606, 2023). "Here, we focus on RhoA, one of the Rho GTPases, and summarize its genetic association with schizophrenia and the effect of RhoA signaling modification in animal models of schizophrenia." (PMID 37958606, 2023). "Several variants in GAPs and GEFs associated with RhoA have been reported to be significantly associated with schizophrenia." (PMID 37958606, 2023). "Furthermore, potential antipsychotic-like effects of RhoA/Rho-kinase inhibitors have been demonstrated in genetic mouse models harboring schizophrenia-associated variants of genes related to RhoA signaling." (PMID 37958606, 2023). "Moreover, several mouse models carrying schizophrenia-associated gene variants involved in RhoA/Rho-kinase signaling have been developed." (PMID 37958606, 2023). "Of note, one schizophrenia patient (Case #5) had a missense variant (p.S490P) in exon 17, which overlapped with an exonic deletion on the other allele and was located in the RhoGAP domain, leading to the activation of RhoA signaling." (PMID 33482876, 2021). "In addition, miR-185 has two validated targets (RhoA, Cdc42), both of which have been associated with altered expression levels in schizophrenia." (PMID 24367288, 2013). "Introduction of these variants, found in individuals with bipolar disorder, schizophrenia, and epilepsy, into GEF2 altered nucleotide exchange rates on RhoA, with some mutations significantly increasing the catalytic activity of GEF2." (PMID 40581118, 2025). "So far, we have reviewed genomic/genetic and reverse translational studies that suggest a role of RhoA signaling in the pathogenesis of schizophrenia." (PMID 37958606, 2023). "Methamphetamine and amphetamine are widely used to induce schizophrenia-like behavior in rodents, and there is evidence that both activate RhoA activity." (PMID 37958606, 2023). "In the last half of the review, we discuss preclinical evidence indicating that RhoA/Rho-kinase is a potential therapeutic target of schizophrenia." (PMID 37958606, 2023). "Growing evidence suggests dysregulation of RhoA signaling contributes to the etiology of multiple psychiatric disorders, including schizophrenia." (PMID 30225353, 2018). "Therefore, the detailed mechanism of RhoA/Rho-kinase signaling in schizophrenia should be further clarified to facilitate the development of safe and effective therapeutic drugs for this disorder." (PMID 37958606, 2023). "In addition, variants in genes that activate RhoA via GEF, such as RTN4R, or in those that degrade RhoA, such as KCTD13, were also identified in schizophrenia." (PMID 37958606, 2023). "Thus, this evidence suggests that RhoA/Rho-kinase signaling is abnormally activated under conditions in which dopaminergic neuronal activity is increased (i.e., schizophrenia)." (PMID 37958606, 2023). "As discussed in this review, RhoA/Rho-kinase is a potential therapeutic target in schizophrenia." (PMID 37958606, 2023). "Recently, several variants of RhoA-associated GAPs, including ARHGAP10, ARHGAP18, and p250GAP, and GEFs such as KALRN and ARHGEF11, were reported to be significantly associated with the development of schizophrenia." (PMID 37958606, 2023). "The reduced miR-185 expression caused deficits in dendritic complexity and spine development in hippocampal neurons, possibly mediated by increased RhoA expression as the two validated miR-185 targets, RhoA and Cdc42, have altered expression levels in schizophrenia." (PMID 35563826, 2022).
schizophrenia (continued). "Dysbindin, a schizophrenia susceptibility marker and an essential constituent of BLOC-1 (biogenesis of lysosome-related organelles complex-1), has recently been associated with cardiomyocyte hypertrophy through the activation of Myozap-RhoA-mediated SRF signaling." (PMID 33142804, 2020). "In particular, rare ARHGAP10 variants are genetically and biologically associated with schizophrenia, and Rho-kinase may represent a promising drug target for schizophrenia treatment in patients with variants of ARHGAP10 and possibly other genes related to the RhoA/Rho-kinase pathway." (PMID 37958606, 2023). "In NPCs and organoids, RhoA signaling and Rho family GTPases pathway were predicted to be inhibited; and both transforming protein RhoA (RHOA) and actin-related protein 2 (ACRT2) were found downregulated in the schizophrenia-patients’ cells." (PMID 36451159, 2022). "Previous studies indicated the morphological abnormality of pyramidal neurons in the frontal cortex of patients with schizophrenia, whereas ARHGAP10 is reported to regulate cellular morphology through the RhoA and Cdc42 pathways in fibroblasts." (PMID 33482876, 2021). "In addition, SMG9 in AD, TCTA in anorexia nervosa, RHOA and IMPDH2 in intelligence, CRHR1 in PD, and PHF7 in schizophrenia are all reported to be conserved among a wide range of species, although their relations with the corresponding traits remain to be explored." (PMID 39905509, 2025). "Although, the importance of ARHGEF11/PSD-95 interaction is not clear in this study, ARHGEF11 (schizophrenia-related gene ARHGEF11) might play a role in glutamate receptor-mediated synaptic plasticity through regulation of RhoA signaling to the actin cytoskeleton." (PMID 28036092, 2016).
airway hyperresponsiveness (9 papers, 2005 to 2023). "RhoA (Ras Homolog Family Member A) is an essential protein associated with smooth muscle contraction in the airways, contributing to developing airway hyperresponsiveness." (PMID 37511254, 2023). "For example, decreases in miR-133a have been linked to increases in RhoA pathway activity in bronchiolar smooth muscle and airway hyperresponsiveness due to IL-13 or IL-17 treatment." (PMID 31511493, 2019). "Downregulation of miR-133a, a muscle miR cocistronic with miR-1, in bronchial smooth muscle correlated with an increase in RhoA and an increase in bronchial smooth muscle contractility associated with airway hyperresponsiveness." (PMID 30046607, 2018). "Ca2+ sensitization due to the RhoA/Rho-kinase processes is involved in airway hyperresponsiveness, which reflects a correlationship between inflammatory cells and airway smooth muscle cells." (PMID 36671004, 2023). "Extracellular ATP acts on P2X (ATP-activated purinergic receptors, different from GPCRs), and contributes to symptoms (dyspnea, wheezing) and the pathophysiology (airflow limitation, airway hyperresponsiveness) via Ca2+ sensitization related to the RhoA/Rho-kinase processes." (PMID 36671004, 2023).
depression (9 papers, 2017 to 2025). "The RhoA/Rho-kinase signaling pathway is thought to be linked to depression, and glucocorticosteroids have been found to affect its expression." (PMID 39684342, 2024). "The RhoA/Rho-kinase signaling pathway appears to be associated with depression, and its expression is influenced by glucocorticosteroids." (PMID 36835228, 2023). "In this module, ADCYAP1R1, PRKACA, MAPK8, MAPK14, GRIA1, and FOS are both targeted genes of CGFC and pathogenic genes of depression; RHOA is a specific targeted gene of CGFC, and most of these genes are related to the pathogenesis or treatment of depression." (PMID 34867413, 2021). "In LPS-induced depression in mice, Saikosaponin D can inhibit hippocampal neuronal apoptosis and inflammation through the lysophosphatidic acid 1/Ras homologous family member A (RhoA)/Rho protein kinase 2 pathway." (PMID 36408279, 2022). "Hence, to understand the mechanism underlying the protective effects of propolis against alcohol-induced intestinal mucosal injury in depression mice, we determined the protein expression of RhoA, and the phosphorylation of LKB1 and AMPK in the jejunum and colon tissue." (PMID 35334870, 2022). "Among GWAS genes that interacted the most with depression portrait genes were the histone acetyltransferase, EP300, the Rho GTPase, RHOA, the heat shock protein HSPA1A, the dopamine receptor, DRD2, the glutamate receptor, GRM5, the huntington gene, HTT, and the estrogen receptor, ESR2." (PMID 33589676, 2021).
endometriosis (9 papers, 2020 to 2025). The growth of functional endometrial tissue in anatomic sites outside the uterine body. "Our prior studies have reported that the abnormal activation of the RhoA/ROCK pathway in endometriosis contributes to the development of the condition by activating the estrogen/ERα/ERK pathway, resulting in EMT and enhanced cell proliferation." (PMID 38735939, 2024). "Abnormal activity of RhoA/ROCKII signaling pathway was demonstrated in eutopic endometrial stromal cells of patients with endometriosis." (PMID 32443784, 2020). "We conclude that abnormal activated RhoA/ROCK pathway in endometriosis is responsible for the function of oestrogen/ERα/ERK signalling, which promoted EMT and proliferation and resulted in the development of endometriosis." (PMID 32725958, 2020). "In this research, we found that the protein expression of Rho/ROCK signalling pathway was abnormally changed in endometriosis and RhoA and ROCK1/2 were remarkably increased in eutopic and ectopic endometria." (PMID 32725958, 2020). "In endometriosis tissues, reduced miR-183 levels lead to increased RhoA and Ezrin expression." (PMID 40630207, 2025). "Furthermore, we found that FTO-mediated m6A mRNA methylation regulates the RhoA pathway, thereby influencing cell migration and invasion in endometriosis." (PMID 40000966, 2025). "The expression status of RhoA/ROCK/Ezrin in endometriosis was verified by animal models." (PMID 40630207, 2025). "Therefore, the increasement of RhoA enhanced EMT, cell mobility and proliferation of human eutopic EECs, which reflected the effect of RhoA/ROCK pathway in endometriosis." (PMID 32725958, 2020). "Endometriosis is considered as an oestrogen‐dependent disorder, and we hypothesized that oestrogen might be an upstream regulator of RhoA/ROCK pathway." (PMID 32725958, 2020). "Thus, oestrogen promoted the development of endometriosis in mouse model and up‐regulated RhoA and phosphorylated ERK." (PMID 32725958, 2020). "Thus, we concluded that RhoA/ROCK pathway was intensively promoted in endometriosis." (PMID 32725958, 2020). "Thus, RhoA/ROCK pathway might be an attractive molecular target in anti‐oestrogen treatment of endometriosis." (PMID 32725958, 2020). "This research attempts to demonstrate the function and molecular mechanism of RhoA/ROCK pathway on epithelial‐mesenchymal transition (EMT) and proliferation in endometriosis." (PMID 32725958, 2020). "To sum up, we conclude that RhoA/ROCK pathway mediated oestrogen/ERα/ERK signalling to promote the EMT and proliferation, resulting in further development of endometriosis." (PMID 32725958, 2020). "In conclusion, this study specifically revealed RhoA/ROCK pathway was up‐regulated by oestrogen/ERα/ERK signalling pathway promoting EMT and proliferation in endometriosis." (PMID 32725958, 2020). "Additionally, the protein expression levels of RhoA, RhoC, and ROCK were markedly reduced in the miR-183 mimic group, indicating that miR-183 markedly inhibited the expression of RhoA, RhoC, and ROCK proteins in endometriosis." (PMID 40630207, 2025). "It is reported that RhoA, RhoC and ROCK1 were significantly higher in ectopic endometrial cells compared with the eutopic endometrial cells in endometriosis, which involved with promoted migration of endometrial cells of endometriosis." (PMID 32725958, 2020). "Consequently, these results suggested that RhoA/ROCK was responsible for the regulation of oestrogen on advancing EMT and proliferation in endometriosis." (PMID 32725958, 2020). "Further researches were performed and found that inhibition of ERK signalling by PD98059 decreased the level of activated RhoA, total RhoA, ROCK1 and ROCK2, which implied ERK pathway might involve with the regulation of RhoA/ROCK pathway in endometriosis." (PMID 32725958, 2020).
endometriosis (continued). "Similarly, genes shared between endometriosis, uterine fibroids, ovarian cancer, migraine and depression (RHOA, FOXP1, ESR1, WNT4, GREB1, FSHB), and endometriosis, migraine and asthma (IGF1, SMAD3, MFHAS1), were enriched in hormone receptor signalling and inflammation pathways, respectively." (PMID 37159502, 2023).
fibrosis (9 papers, 2008 to 2024). the formation of excess fibrous connective tissue in an organ or tissue in a reparative or reactive process. "We have also observed that atorvastatin ameliorates vascular fibrosis caused by AngII, by a process regulated by RhoA and MAPK activation." (PMID 19088845, 2008). "Therefore, this study provides new evidence that HPM ameliorates CD-associated intestinal fibrosis by inhibiting RhoA and ROCK1 proteins." (PMID 34840583, 2021). "Our accumulated data suggest that SLIT3 significantly regulates Ang II-induced cardiac fibrosis and fibroblast differentiation via the RhoA/ROCK1 signaling pathway." (PMID 38800023, 2024). "Similarly, a recent study using aged rats showed that the RhoA/ROCK1/LIMK2/Cofilin pathway was involved in cavernosal fibrosis and ED caused by advanced age, suggesting that these factors might be novel targets in the treatment of age-related cavernosal fibrosis." (PMID 30870492, 2019). "It is well established that the RhoA signaling pathway is critically involved in cardiac fibrosis." (PMID 32351730, 2020). "Therefore, SLIT3 could significantly affect cardiac fibrosis and fibroblast differentiation through the RhoA/ROCK1 pathway." (PMID 38800023, 2024). "A RhoA inhibitor decreased accumulation of macrophages and neutrophils in the airways of BLM-treated mice and also BLM-induced fibrosis." (PMID 24970330, 2014).
lymph node metastasis (9 papers, 2013 to 2025). "Enhanced immunoreactivity of all analysed proteins was found to be associated with the presence of lymph node metastases (ezrin, P = 0.047, moesin, P = 0.038, RhoA, P = 0.024, RhoB, P = 0.004 and Cdc42, P = 0.047)." (PMID 23420497, 2013). "In our study, over-expression of RhoA, RhoB and Cdc42 was found to be strongly associated with the presence of lymph node metastases." (PMID 23420497, 2013). "In addition, the reduction of RhoA was associated with lymph node metastasis and shorter survival in an analysis of 137 colorectal tumor samples." (PMID 32244355, 2020). "In a multivariate analysis, which included ARHGAP25, RhoA, lymph node metastasis (LNM), and TNM stage as covariates, the presence of VM increased the risk of death (multivariate HR 1.872, 95% CI: 1.195-2.933, p=0.006)." (PMID 40786517, 2025). "Since AHR, RhoA and ROCK1 were all associated with lymph node metastasis and clinical stage, and they correlated significantly with each other, we wondered if they had any relationships with overall survival time." (PMID 32546278, 2020). "Notably, decreased reactivity of RhoA in the tumour stromal compartment was correlated with the presence of lymph node metastases (P = 0.011)." (PMID 23420497, 2013). "We found that higher levels of CXCR4, RhoA, RhoGEF, PI3K, and ROCK correlated positively with TNM stage (p < 0.05) and lymph node metastasis (p < 0.05) but not with age, gender, tumor size or tumor differentiation." (PMID 27517626, 2016).
portal hypertension (9 papers, 2012 to 2024). Increased blood pressure in the portal venous system. "In addition, RhoA-related signalling pathways have been shown to be closely linked to human liver cirrhosis and related complications such as portal hypertension." (PMID 32496208, 2020). "In the present study, to investigate the effects of SF on fibrosis, portal hypertension and the RhoA/Rho-kinase pathway, hepatic cirrhosis was induced in rats by bile duct ligation." (PMID 25174394, 2014). "Cirrhotic rats show higher expression levels of hepatic RhoA and Rho-kinase than normal healthy rats, and the activation of this signaling pathway leads to portal hypertension." (PMID 25174394, 2014). "Therefore a drug that blocks cholesterol synthesis at a site upstream from GGPP formation may have the potential to block the RhoA/Rho-kinase pathway and thus attenuate portal hypertension." (PMID 25174394, 2014). "In the present study, we hypothesized that SF, which decreases the synthesis of GGPP, a compound essential for RhoA activation and initiation of the RhoA/Rho-kinase pathway in HSCs, would ameliorate fibrosis and portal hypertension in rats with secondary biliary cirrhosis." (PMID 25174394, 2014). "It is well known that in cirrhosis activated RhoA/ROCK-2 signaling and inhibited nitric oxide (NO) availability contribute to increased intrahepatic resistance and portal hypertension." (PMID 22479572, 2012). "In summary, these data suggest a greater role of Shh/RhoA-signaling in the extrahepatic angiogenesis in cirrhosis, whereas Gli-2 is a predominant mediator of canonical Hh-pathway in non-cirrhotic portal hypertension." (PMID 26412302, 2015). "Therefore, the aim of the present study was to investigate the effect of chronic spironolactone treatment on intrahepatic RhoA/ROCK-2 signaling and NO/PKG pathway as well as on lilver fibrosis and portal hypertension." (PMID 22479572, 2012). "Moreover, carvedilol inhibited Ang II-induced HSC contraction by interfering with the AT1R-mediated RhoA/ROCK2 pathway, which may be one of its molecular mechanisms for reducing portal hypertension." (PMID 31828132, 2019).